BAX (BCL2 associated X, apoptosis regulator)
Diseases named in the same sentence as BAX in open-access papers (continued):
Sharing a sentence is not in itself a finding about the gene and the disease.
endometriosis (10 papers, 2014 to 2026). The growth of functional endometrial tissue in anatomic sites outside the uterine body. "pAKT (phosphorylated AKT), γH2AX, BIM, and BAX were overexpressed in EAOCs and contiguous endometriosis as compared to benign endometriosis (p < 0.05), while pATM, pCHK2, and Bcl2 were downregulated." (PMID 40364006, 2025). "reuteri alone did not alter endometriosis-related proteins, but in the presence of E2G, it reduced BAX/Bcl-2 ratios and increased p-NF-κB, suggesting anti-apoptotic and pro-inflammatory shifts." (PMID 42089668, 2026). "Despite the presence of some tendencies, we saw no significant changes in the expression of BCL-2-associated X protein (BAX) and B-cell lymphoma-X short and long isoforms (BCL-XS and BCL-XL) in the ovaries of rats with and without endometriosis." (PMID 40002761, 2025). "In addition, rutin, one of the flavonoids of Codium fragile, inhibited apoptosis by regulating the expression of BCl-2/BAX ratio, Caspase-9, and cleaved poly ADP-ribose polymerase (PARP) in endometriosis development in a rat model." (PMID 37760047, 2023). "Evaluation of apoptosis-related genes showed that E-MenSCs significantly decreased mRNA expression of BAX (proapoptotic gene) (0.052 fold, P = 0.05) and significantly increase mRNA expression of BCL-2 (antiapoptotic gene) (1.60 fold, P = 0.01) in endometriosis cells, as compared with NE-MenSCs." (PMID 35059465, 2022). "Interestingly, endometriosis-like lesions developed in MIF-KO mice showed a significant down-regulation of BCL2, which promotes cell survival, but no noticeable change in the expression of the apoptotic BCL2-family member BAX, which binds to BCL2 and counteracts its apoptosis-preventing effects." (PMID 25329068, 2014).
non-small cell lung carcinoma (10 papers, 2014 to 2025). A group of at least three distinct histological types of lung cancer, including non-small cell squamous cell carcinoma, adenocarcinoma, and large cell carcinoma. "Elevated levels of lncRNA GHRLOS significantly inhibited cancer cell proliferation and invasion while promoting apoptosis through the modulation of E-cadherin, N-cadherin, BAX, and Bcl-2 expression in non-small-cell lung cancer." (PMID 39940682, 2025). "Chalcomoracin, which has a strong affinity for BAX, has been shown to inhibit cell proliferation through endoplasmic reticulum stress-mediated paraptosis and to increase the sensitivity of non-small cell lung cancer to radiotherapy." (PMID 38439022, 2024). "For instance, it has been reported that lncRNA BANCR enhances the level of apoptosis in NSCLC (non-small cell lung carcinoma) cell lines in vivo by modulating the expression of Bcl-2 and BAX." (PMID 32499679, 2020). "In another study, BCP of chili pepper was found to inhibit non-small cell lung cancer (NSCLC) growth, and to promote their apoptotic rate and increase the level of apoptotic markers (cleaved caspase-3 and BAX) and anti-oxidant factors (SOD, CAT and GPx)." (PMID 36500446, 2022).
Stroke (10 papers, 2018 to 2025). Sudden impairment of blood flow to a part of the brain due to occlusion or rupture of an artery to the brain. "Additionally, an acute insult such as ischemia or stroke would only require transient BAX inhibition, further limiting risk to cancer development." (PMID 33162554, 2021). "Deficiency of PUMA and/or BAX is sufficient to prevent neuronal cell death in response to oxidative stress, ER stress, DNA damage, environmental toxins, proteasomal inhibition, stroke-like stress, trophic-factor deprivation, pan-kinase inhibition, and death receptor activation." (PMID 33162554, 2021). "A previous study in post-stroke mice demonstrated that Com-B exerts its anti-apoptotic effects on hippocampal neurons by regulating the expression of BAX/BCL-2 and caspase-3." (PMID 40649809, 2025). "This time period provides a unique opportunity for a BAX inhibitor to limit the amount of cell death following stroke." (PMID 33162554, 2021). "Outside of the necrotic core of the infarct in stroke, neurons within the penumbra die from delayed apoptosis, which can be prevented in mouse models by the genetic deletion of BAX." (PMID 33162554, 2021). "Given the emergence of these inhibitors, the question remains if pharmacological BAX inhibition protects against neurological events such as stroke." (PMID 33162554, 2021). "Stroke increased the mRNA and protein expression of BAX under room air after 2 and 6 hours of reperfusion, while under NBO, an increase in BAX was significantly inhibited (p < 0.05)." (PMID 34306153, 2021). "Our data are also in line with other authors who have demonstrated ischemia-induced increases in Fas, Caspase-3, BAX and AhR protein levels in in vitro and in vivo models of stroke." (PMID 30778709, 2019). "The combination group treated at 4.5 h after ischemia was significantly reduced the expression of BAX and caspase-3 mRNA, as same as the combination group treated at 2 and 4 h after stroke." (PMID 29681849, 2018). "Moreover, the Bcl-2/BAX ratio in the stroke groups was 0.4 at both 1 and 3 days but significantly increased in both IPostE (***p < 0.001, 1.8 at 1 day and 0.9 at 3 days) and MPostE groups (***p < 0.001, 2.2 at 1 day and 1.9 at 3 days)." (PMID 33664650, 2021). "After stroke, the expression of BAX and caspase-3 mRNA was significantly upregulated." (PMID 29681849, 2018). "In order to determine the Danhong injection plus t-PA prolonged the thrombolytic window to 4.5 h for treatment of focal embolic stroke in rats, real time RT-PCR was performed to determine the relative levels of BAX, Bcl-2, and caspase-3 mRNA transcriptions in rat tissue." (PMID 29681849, 2018). "CWDD has a significant effect on the recovery of cognitive function and depressive mood in stroke patients after stroke which may be related to the activation of PI3K/AKT-mediated Bcl and BAX pathway." (PMID 35712089, 2022). "Genetic deletion of BAX does not prevent cell injury but has been shown to prevent neuronal cell death in mouse models of stroke and traumatic brain injury." (PMID 33162554, 2021). "Furthermore, our data demonstrated that TGR5 knockdown significantly reverses the neuro-protection of TUDCA on stroke outcomes, as well as increasing BCL-2 and decreasing BAX and cleaved caspase-3 expression." (PMID 33261652, 2020).
adenoma (9 papers, 2016 to 2022). A neoplasm arising from the epithelium. "The positive association with BAX led to an inverse association for the BCL2/BAX ratio with increasing adenoma size (p-trend<0.0001)." (PMID 34762658, 2021). "Further, the tumor suppressor genes, SMAD2, SMAD4, and BAX, were also involved in the late adenoma stage." (PMID 36499586, 2022). "Among adenomas, cyclin D1 LI and p16 LI levels increased with greater villous component, and the highest BAX expression was detected in adenomas larger than 2 cm (both p<0.0001)." (PMID 34762658, 2021). "Adenomas also displayed higher pro-apoptotic BAX and anti-apoptotic BCL2 expression compared to serrated lesions." (PMID 34762658, 2021). "Lower levels of BAX have also been reported in HPPs compared to other types of serrated lesions as well as adenomas." (PMID 34762658, 2021). "Clear contrast ofBAX is frequently inactivated correlates to pore prognosis; there areno significant differences of BAX between goiters or adenoma." (PMID 31285648, 2019). "Among tubular adenomas, none of the apoptosis regulators except BAX was associated with adenoma size (p-trend<0.0001)." (PMID 34762658, 2021). "BAX staining levels were markedly higher in adenomas and carcinomas than in normal mucosa." (PMID 28035578, 2017). "In non-functioning adenomas as well as in PRL-secreting adenomas the expression of Bcl-2 found decreased and BAX protein was increased when associated with pituitary tumor progression." (PMID 29104246, 2017). "Moreover, the BAX level was higher in carcinomas than in adenomas." (PMID 28035578, 2017). "Cyclin D1 LI, p16 LI and p21 LI were lower in adenomas compared to serrated lesions, while expression of both BCL2 and BAX were higher (p <0.001)." (PMID 34762658, 2021).
COVID-19 (9 papers, 2020 to 2024). A disease caused by infection with severe acute respiratory syndrome coronavirus 2. "There was a significant increase in the transcripts of these cytokines as well as Bcl-2 associated protein X (BAX), a pro-apoptotic gene, in HTO exposed to COVID-19 plasma." (PMID 37200377, 2023). "The rete testis area presented degenerating germ cells, and BAD and BAX levels were augmented in nearly all COVID-19 patients." (PMID 36797789, 2023). "Meanwhile, the correlation analysis of ICD-related DEGs and immune cell infiltration in severe COVID-19 showed that TLR4, PIK3CA, FOXP3, ENTPD1, CD4, CASP1 and BAX were significantly correlated with a variety of immune cell infiltration." (PMID 38600309, 2024).
myocardial infarction (9 papers, 2017 to 2025). Gross necrosis of the myocardium, as a result of interruption of the blood supply to the area, as in coronary thrombosis. "The MST1-mediated BECLIN1 phosphorylation that enhances the BECLIN1:BCL-2 interaction to reduce autophagy also consequently reduces the interaction between BCL-2 and BAX, causing BAX activation and stimulation of apoptosis during myocardial infarction." (PMID 34204202, 2021). "Direct targeting of BAK/BAX to inhibit cardiomyocyte apoptosis and necroptosis is an effective approach to improve the poor prognosis of myocardial infarction." (PMID 41514922, 2025). "A research has shown that miR-298 can regulate apoptosis in myocardial infarction by targeting BAX (Zhang, Yu & Yu, 2018)." (PMID 39650552, 2024). "BAX, c-caspase-3 and myocardial infarction area were elevated (P<0.05)." (PMID 32347295, 2020). "BAX, c-caspase-3 and myocardial infarction area were decreased (P<0.05)." (PMID 32347295, 2020). "We explain how various signals during a heart attack converge to activate BAK and BAX, leading to irreversible damage." (PMID 41514922, 2025). "Focusing on apoptosis and mitochondrial-permeability transition pore (MPTP)-driven necrosis in myocardial infarction, this review highlights the therapeutic potential of inhibiting the core effectors BAK and BAX to limit cell death and improve outcomes." (PMID 41514922, 2025). "In addition, targeted delivery of BAK/BAX inhibitors to cardiomyocytes during AMI or myocardial IR has the potential to reduce myocardial cell death and therefore lower the mortality and enhance long-term prognosis for myocardial infarction patients." (PMID 41514922, 2025).
Parkinson disease (9 papers, 2009 to 2025). A progressive degenerative disorder of the central nervous system characterized by loss of dopamine producing neurons in the substantia nigra and the presence of Lewy bodies in the substantia nigra and locus coeruleus. "Alternative targets for miR-216a-5p include the transcription factor FoxO1, which is related to the human mesangial cell proliferation in diabetic nephropathy, and BAX, which is associated with the protection neurons from apoptosis in Parkinson’s disease." (PMID 33415108, 2020). ", who proposed that KYNA exerts neuroprotection in an in vitro model of Parkinson’s disease at least in part due to the down-regulation of BAX expression." (PMID 39153038, 2024). "By targeting BAX, some miRNAs like MicroRNA-216a also inhibit neuronal cell apoptosis in Parkinson’s disease." (PMID 35269511, 2022). "Specifically, proteins in the BCL2 family, such as BAX, can mediate the apoptosis of dopaminergic neurons in the Parkinson’s disease." (PMID 35269511, 2022). "A study investigated that inhibition of ITGA7 down-regulated the expression of BCL2 and increased the BAX/BCL2 ratio, causing apoptosis of SH-SY5Y cells in Parkinson’s disease mouse models." (PMID 36204112, 2022). "The detected proteins are involved in a wide range of diseases; spastic paraplegia (HSPD1), cancer (BAX, PHB), optic atrophy (OPA1), ethylmalonic encephalopathy (ETHE1) and Parkinson's disease (NDUFV2)." (PMID 19476632, 2009). "It is well known that MOAP1 directly binds to BAX, which suggests that MOAP1 may play a role in Parkinson’s disease." (PMID 35269511, 2022). "In this regard, BAX, another member of the BCL2 gene family, immunolocalizes in lysosomes in a variety of cell lines exposed to pro‐apoptotic stimuli and in experimental models of Parkinson's disease, where it has been shown to induce lysosomal membrane permeabilization and lysosomal dysfunction." (PMID 35263007, 2022).
Sepsis (9 papers, 2009 to 2025). Sepsis is defined as life-threatening organ dysfunction caused by a dysregulated host response to infection. "In sepsis mice with high hearing loss BAX was distributed mainly in type I, II, and V fibrocytes, root cells, outer and inner hair cells and supporting cells were strongly stained." (PMID 28404559, 2017). "In sepsis mice with high hearing loss a higher reactivity of BAX (14.96) than in sepsis mice with low hearing loss (11.94) was shown, while only a moderate staining was observed in sham mice (4.91)." (PMID 28404559, 2017). "A significant activity of BAX (P=0.027) and CC-3 (P=0.024) in sepsis mice with a high hearing loss could be found." (PMID 28404559, 2017). "In our study, we indicate that the expression levels of the ER stress markers p-eIF2α and GRP78 and two factors involved in ERS-related apoptosis, CHOP and Caspase-3, were increased, and the BCL-2 : BAX ratio was decreased during sepsis." (PMID 31263382, 2019). "In the sepsis mice discrete labelling of BAX in the utricle and ampulla was found." (PMID 28404559, 2017). "In sepsis-induced acute lung injury, upregulation of lncRNA H19 inhibited TNF-α, IL-1β, IL-6, IL-10, and BAX to suppress pulmonary apoptosis and inflammation." (PMID 39940682, 2025). "Curcumin in sepsis reduced cerebral mitochondrial dysfunction (MMP, ROS, and mitochondrial complex activity I), apoptosis in neurons, and expression of BAX and increased the expression of BCL-2." (PMID 36756300, 2023). "Studies have proved that the BAX expression of lung is increased and BCL-2 expression of lung is decreased in sepsis-induced ALI model in mice." (PMID 27807512, 2016). "Our results raised the possibility that YAP/P73/(BAX and BCL-2)/caspase-3 pathway played an important role in regulating HPMEC apoptosis in sepsis-induced ALI." (PMID 27807512, 2016). "Treatment with SP600125 decreased BAX expression and enhanced BCL-2, thus suggesting the specific JNK inhibitor blunts the activation of proapoptotic signal in polymicrobial sepsis." (PMID 25873765, 2015).
B cell lymphoma (8 papers, 2012 to 2025). "The BCL-2-associated X protein (BAX) to B-cell Lymphoma/Leukemia (BCL2) ratio was assessed by qRT-PCR." (PMID 41354896, 2025). "Our findings are consistent with recent studies which found that loss of BAX could confer resistance to both venetoclax and S63845 in AMLs and a panel of non-Hodgkin B cell lymphoma cell lines." (PMID 36755070, 2023). "Among the pro-apoptotic proteins of the BCL2 family, BAX has a crucial role in apoptosis and the lack of BAX leads to apoptosis impairment and facilitates the development of B-cell lymphoma by c-Myc stimulation." (PMID 22300941, 2012). "Interestingly, BAX knockout in B-cell lymphoma cells did not result in decreased VEN-sensitivity, further indicating that BAX-deficiency (due to gene alteration or other mechanisms) on its own impairs VEN-sensitivity in some contexts but does not seem to be a general mechanism of VEN-resistance." (PMID 38961053, 2024).
Hyperglycemia (8 papers, 2018 to 2024). An increased concentration of glucose in the blood. "Previous research has shown that hyperglycemia causes mesangial cell death via oxidative stress and inflammation, marked by an increase in the BAX/Bcl-2 ratio." (PMID 37016650, 2023). "The current study showed that hyperglycemia results in a significant upregulation of the proapoptotic BAX gene and downregulation of the antiapoptotic Bcl-2 gene, as well as increased BAX/Bcl-2 ratio in the testes of the diabetic rats." (PMID 34458667, 2021). "Since BAX-induced apoptosis enhances immune tolerance, we evaluated whether increasing BAX plasmid content of our ADi-100 formulation could enhance the efficacy in reversing hyperglycemia in mildly hyperglycemic female NOD mice." (PMID 32143316, 2020). "Moreover, mitochondrial membrane permeability, estimated by mRNA expression of BAX, which is a component of the permeability transition pore, was increased in hyperglycemia environment, and this effect was accompanied by the upregulation of mtDNA in the mitochondria-free cytosol." (PMID 39349450, 2024). "The overexpression of BAX inhibitor-1 could inhibit IRE and reversed hyperglycemia in diet-induced obesity mice." (PMID 35465608, 2022).